NOTCH2 (notch receptor 2)
Diseases named in the same sentence as NOTCH2 in open-access papers (continued):
Sharing a sentence is not in itself a finding about the gene and the disease.
breast cancer (continued). "Accordingly, protein levels of E-cadherin were up-regulated and accumulation of N-cadherin and vimentin was abolished after knock-down of Notch2 in irradiated MCF7 breast cancer cells." (PMID 27462787, 2016). "Collectively, these findings suggest that Notch2 regulates radiation-induced EMT responses via the NICD2 domain in breast cancer cells." (PMID 27462787, 2016). "While the compound attenuated the activation of Notch-1 in colon cancer and human breast cancer cells, it activates the cleavage of Notch-2 and Notch-4 in human breast cancer (MDA-MB-231) cells." (PMID 26959007, 2016). "Notch1 and Notch2 fusion transcript, retaining the exons that encode the Notch intracellular domain (NICD,) was subsequently described in breast cancer." (PMID 28036048, 2016). "Although most studies have been utilized Notch1 as the readout of Notch signaling, the four Notch receptors, Notch1, Notch2, Notch3 and Notch4, are thought to have different functions in breast cancer." (PMID 25229616, 2014). "Grouped by gene, many of these novel mutations comprised large gains in absolute counts and in percent increase, including MAP3K1 and GATA3 in breast cancer, and NOTCH2 and CDKN2A in lung cancer." (PMID 24970867, 2014). "Conversely, Notch2 is a new tumor suppressor; it inhibits tumor progress in human breast cancer and small cell lung cancer." (PMID 23599800, 2013). "Activation of Notch2 by overexpression of its intracellular domain has been shown to promote apoptosis in MDA-MB-231 human breast cancer cells." (PMID 22970326, 2012). "In breast cancer, Notch2 pathway is also a potent pro-apoptotic signaling with inhibitory effect on tumor growth in xenograft model." (PMID 22439831, 2012). "Real-time PCR and Western blot analysis were performed to detect Notch-1, Notch-2, Notch-3 and Notch-4 receptor expression in breast cancer cells when PEA3 was knocked down by siRNA." (PMID 21679465, 2011). "Further studies are needed to investigate possible mechanisms of regulation of NOTCH2 expression by rs11249433 and the role of NOTCH2 splicing forms in breast cancer development." (PMID 20482849, 2010). "Western blot analysis showed that both NOTCH1 and NOTCH2 were expressed at different degrees in six human breast cancer cell lines." (PMID 20010940, 2010). "Consequently, targeting NOTCH2 signaling is under investigation as a therapeutic strategy to combat resistance in various cancers, including breast cancer, lung cancer, and chronic lymphocytic leukemia." (PMID 40507238, 2025). "Breast cancer cells showed cytoplasmic immunostaining for Jagged-1, Notch-1, Notch-2, and HERP-1." (PMID 38314334, 2024). "Based on the CNV data, several special CNV regions were identified, including gain peaks containing known breast cancer driver genes such as ERBB2 and NOTCH2, as well as the loss peaks containing some known tumor suppressor genes such as PRDM16 and STK11 (CNV focal peak gene annotation)." (PMID 35013309, 2022). "Finally, we investigated the expression of Notch2 in samples from a cohort of bone metastatic breast cancer patients both in primary tumours and matched bone metastases." (PMID 31239543, 2019). "The purpose of this up-to-date review is to provide a detailed overview of the specific role of all four Notch receptors (Notch1, Notch2, Notch3, and Notch4) in TNBCs, thus identifying the Notch signaling pathway deregulation/activation as a pathognomonic feature of this breast cancer subtype." (PMID 31379945, 2019). "However, analysis of public data sets showed a better survival in patients bearing breast cancers expressing higher levels of Notch2, which was even more prominent in untreated patients or in patients treated with endocrine therapy." (PMID 31239543, 2019). "The role of Notch2 in breast cancer is less well characterized with respect to Notch1." (PMID 31379945, 2019). "Notch2/3 inhibition (Tarextumab) decreased CSC numbers in the UM-PE13 breast cancer cells." (PMID 30515368, 2018).
breast cancer (continued). "Withaferin-A-mediated inhibition of MDA-MB-231 cell migration was significantly augmented by knockdown of Notch-2 and Notch-4 protein, suggesting that the Notch-2 and Notch-4 activation by withaferin-A impairs its inhibitory effect on breast cancer cell migration." (PMID 26959007, 2016). "A role of Notch2 and Akt in breast cancer progression was also supposed." (PMID 28036048, 2016). "Collectively, our findings suggest that Notch2 could be a therapeutic target of efforts to overcome radiotherapy induced relapse in the breast cancer treatment." (PMID 27462787, 2016). "Finally, we defined the molecular basis of radiation-induced EMT in breast cancer cells, finding that it results from the fact that Notch2 upregulation is accompanied by IL-6-dependent STAT3 activation." (PMID 27462787, 2016). "However, further studies are needed to investigate possible mechanisms of regulation of NOTCH2 expression by rs11249433 and the role of NOTCH2 splicing forms in breast cancer development." (PMID 23977314, 2013). "This assumption is also supported by the fact that miR-34b is predicted (miRWalk Database) as a direct regulator of Notch2 which plays an important role in cell differentiation and is decreased in breast cancer tumors with poor differentiation (Grade 3) and a worse prognosis." (PMID 22439831, 2012). "With the addition of the epithelial–mesenchymal transition as a mechanism driving the formation of metaplastic spindle cell tumours, a process which may also be regulated by NOTCH2, a model of the differentiation pathways that drive mammary tumour heterogeneity can begin to be built." (PMID 37686600, 2023). "In addition, Notch2 was found could inhibit tumor growth, and continuous activation of N2ICD increases apoptosis in human breast cancer cells." (PMID 36139447, 2022). "Our findings also suggest that NOTCH1 and NOTCH2-driven breast cancers may represent a distinct biological form of breast cancer that is driven in part through the silencing of the PTEN tumor suppressor gene, in addition to the activation of oncogene targets such as MYC56." (PMID 33750924, 2021). "In the overall analysis, except for rs11249433 which is in close proximity to NOTCH2 gene that showed significant association with breast cancer, none of the other SNPs were found to confer increased risk either in breast or colorectal cancers in our population." (PMID 34257585, 2021). "Notably, although activation of Notch2 induced higher vascularization, the vessels were smaller and comprised a more immature network as compared with Notch4-activated signaling, suggesting its suppressive role in the angiogenesis of breast cancer." (PMID 33919109, 2021). "Previous studies have shown that Notch2 signaling could play a protective role in breast cancer." (PMID 28659656, 2017). "In addition, no NICD1 staining was seen in sections of the MCL cell line MAVER-1, which has wild type NOTCH1 alleles and is devoid of NICD1, or in the breast cancer cell line HCC1587, which has wild type NOTCH1 alleles and instead has an activating deletion involving NOTCH2." (PMID 23825651, 2013). "Similar association between NOTCH2 expression and rs11249433 was observed in 60 samples of purified monocytes from healthy controls (p = 0.015), but not in total blood samples from 302 breast cancer patients and 76 normal breast tissue samples." (PMID 20482849, 2010). "A decrease of NOTCH2 serum levels with E+P, but not E-alone, could be related to alteration of signaling and increased risk of breast cancer with E+P but not with E-alone." (PMID 20034393, 2009). "Its role in breast cancer as a potential serum biomarker for brain metastasis and its involvement in NSCLC progression through the LINC01806/miR-4428/NOTCH2 axis further underscore its multifaceted functionality." (PMID 40282289, 2025).
breast cancer (continued). "In other malignancies, such as gastric cancer and breast cancers, NOTCH receptor expression is a good prognostic indicator of residual disease, where low NOTCH2 expression in residual tumours is correlated with longer survival times." (PMID 36982928, 2023). "The expression of NOTCH-1, NOTCH-2, and NOTCH-3 was compared in each breast cancer molecular subtype." (PMID 36476410, 2022). "Notch receptors (NOTCH-1, NOTCH-2, and NOTCH-3) are highly expressed in basal/claudin-low breast cancer subtypes." (PMID 36476410, 2022). "The up-regulation of both NOTCH-2 and NOTCH-3 were correlated with longer survival rates in breast cancer patients." (PMID 36476410, 2022). "In 2015, Kim and co-workers reported that 1 exhibited anticancer activity against breast cancer stem-like cells by reducing the expression of CD44, Oct4, Notch2, β-catenin and Sox2 proteins." (PMID 35209235, 2022). "Using breast cancer cell lines, we found that mutant forms of NOTCH1 or NOTCH2 collaborate with EZH2 to mediate the transcriptional repression of PTEN in these poor-prognosis breast cancers." (PMID 33750924, 2021). "We show that repression of PTEN occurs through the combined action of NOTCH (NOTCH1 or NOTCH2) and EZH2 alterations in a subset of breast cancers." (PMID 33750924, 2021). "Preliminary activity against Notch has been further demonstrated by using tarextumab, a first-class anti-Notch2/3 antibody, in a recently completed phase I clinical trial for the treatment of advanced solid tumors (NCT01277146), including breast cancer." (PMID 35582386, 2021). "The NOTCH family genes, including NOTCH1, NOTCH2, NOTCH3, and NOTCH4, are highly expressed in breast cancer patients." (PMID 33324444, 2020). "The inhibition of Notch2 activation attenuated the radiation-induced invasive and migratory properties of MCF7 breast cancer cells and recovered the E-cadherin protein levels with the down-regulation of N-cadherin, vimentin and NICD2." (PMID 27462787, 2016). "In Chinese population, while the association of NOTCH2-rs11249433 and NOTCH3-rs1043994 was lacking with breast cancer risk, NOTCH1-rs3124591 was significantly associated with invasive ductal carcinoma and ductal carcinoma in situ." (PMID 34257585, 2021). "In contrast, breast cancer cells expressing a constitutively active truncated Notch2 protein, which does not include the S3-cleavage site (HCC1187), do not depend on endocytosis and are unaffected by V-ATPase inhibition." (PMID 34572582, 2021). "This hypothesis was confirmed by in vitro experiments showing that breast cancer cells plated on SNO cells reduced their own proliferative rate and expressed high level of Notch2." (PMID 30867009, 2019). "In particular, Kim and colleagues revealed that treatment of MCF-7, MDA-MB-231, and SUM159 human breast cancer cells with Benzyl isothiocyanate (BITC), a constituent of cruciferous vegetables, increases levels of the active form of Notch1, Notch2, and Notch4 in both cultured and xenografted cells." (PMID 31379945, 2019). "In addition, several proteins were identified by KM plotter as potential drug targets, such as S100P, carbonic anhydrase IX (CAIX), Notch1 in breast cancer, aldehyde dehydrogenase 1 (ALDH1) in NSCLC, Notch2 in ovarian cancer." (PMID 28061457, 2017). "Moreover, Notch2 activation by ZER inhibits its proapoptotic and anti-migratory response in breast cancer cells." (PMID 27158037, 2016). "Activating deletions in either NOTCH1 or NOTCH2 have been identified in a minority of breast cancers, most of which are triple-negative (ER/PR/HER2 negative) tumors." (PMID 23825651, 2013). "Researchers had proved that miR-1296-5p could function as an inhibitor in gastric cancer by targeting cyclin-dependent kinase 6 and epidermal growth factor receptor, ERBB2-positive breast cancer by downregulating ERBB2, in osteosarcoma through repressing notch receptor 2 expression." (PMID 35287543, 2022).
breast cancer (continued). "Dormant breast cancer cells compete with long-term hematopoietic stem cells for the occupancy of the endosteal niche, which is enriched in spindle-shaped N-cadherin+/CD45− osteoblasts (SNOs) and keeps tumor cells in quiescent state in a Notch2-dependent manner." (PMID 35994202, 2022). "Intriguingly, Notch2 and its ligand, Jagged-1, could also upregulate HES1 expression to inhibit miR-205-5p, and constituted a negative feedback loop of Notch2/miR-205-5p/ZEB1 signaling in breast cancer cells." (PMID 31752366, 2019). "Furthermore, NOTCH2 and NOTCH3 amplifications are found in basal breast cancers." (PMID 30388742, 2018). "To this end, when MCF7 breast cancer cells were treated with a STAT3 inhibitor or DMSO and radiated afterwards, we observed that the inactivation of STAT3 sharply attenuated the radiation-induced Notch2 (NICD2), Jagged1 and DLL4 mRNA expression and protein levels." (PMID 27462787, 2016). "We also observed a significant negative correlation between NOTCH-1, NOTCH-2, and NOTCH-3 expression and their methylation, suggesting a potential epigenetic regulation of Notch receptors in breast cancer." (PMID 36476410, 2022).
Alagille syndrome (68 papers, 2008 to 2026). "Mutations in notch ligand JAG1 or receptor NOTCH2 harbors a rare autosomal dominant genetic disorder, namely Alagille syndrome (ALGS), which is characterized by intrahepatic bile duct paucity in infants and children, leading to jaundice and cholestasis." (PMID 39747668, 2025). "Notch signaling patterns the cochlear organ of Corti, and individuals with the JAG1/NOTCH2-related genetic disorder Alagille syndrome can thus experience hearing loss." (PMID 39373109, 2024). "Haploinsufficiency of Notch signaling pathway has been demonstrated to cause CS and mutations in NOTCH2 caused Alagille syndrome and Hajdu–Cheney syndrome, both of which showed abnormal curvature of the spine." (PMID 34440387, 2021). "Notch2 and Notch3 are also associated with disease—Alagille syndrome and leukoencephalopathy, respectively." (PMID 34677194, 2021). "JAG1 variants are observed in ∼90% of Alagille syndrome patients whereas NOTCH2 variants account for additional 1–2% of individuals with Alagille syndrome." (PMID 33585486, 2021). "For example, mutations in genes of this signaling pathway, such as Jagged1 and Notch2 have been identified as the cause of defects in IHBD development in patients with Alagille syndrome." (PMID 34187572, 2021). "For instance, syndromic CHD such as Alagille syndrome is caused by a single-gene defect (a variation in the Notch2 gene)." (PMID 34677194, 2021). "Many of the features associated with Alagille syndrome have been recapitulated in heterozygous Jag1 mice, but double heterozygous Jag1 and Notch2 mice more closely approximated the phenotypes seen in humans." (PMID 32161758, 2020). "Whole exome sequencing (WES) identified a paternally inherited RASA1 heterozygous pathogenic variant p.(Ser219Ter) causing CM-AVM and a de novo NOTCH2 heterozygous variant p.(Met2042Thr) associated with Alagille syndrome." (PMID 31749841, 2019). "Combining our cohort of 86 novel JAG1 and three novel NOTCH2 variants with previously published data (totaling 713 variants), we present the most comprehensive pathogenic variant overview for Alagille syndrome." (PMID 31343788, 2019). "Mutations in JAG1 or Notch2 are known causes of Alagille syndrome, an autosomal dominant disease characterized by congenital cholangiopathy with jaundice and bile duct paucity." (PMID 30643196, 2019). "Autosomal dominant mutations in NOTCH1 cause the Adams–Oliver syndrome (OMIM 616028), while autosomal dominant mutations in NOTCH2 are reported in the Alagille syndrome 2 (OMIM 610205) and in the Hajdu–Cheney syndrome (OMIM 102500)." (PMID 31555317, 2019). "In humans, loss-of-function mutations in Notch2 or its ligand Jagged1 are associated with Alagille Syndrome, a developmental disorder leading to bile duct scarcity." (PMID 29545603, 2018). "NOTCH2 mutations are found in about 1% of the cases of Alagille syndrome, a severe developmental disorder defined clinically by hepatic bile duct paucity and cholestasis in association with cardiac, skeletal, and ophthalmologic manifestations." (PMID 23597238, 2013). "It is also known that heterozygous mutations in NOTCH2 can cause Alagille syndrome (OMIM#610205) and Hajdu-Cheney syndrome (OMIM #102500)." (PMID 22662265, 2012). "The first CNV detected in our patient (1p12 deletion) results in a deletion of part of the NOTCH2 gene that can be mutated in Alagille syndrome, a multisystem disorder with predominantly liver-, skeletal, ophthalomologic and renal abnormalities." (PMID 22830313, 2012). "Mutations in gene encoding NOTCH2 leads to Alagille syndrome, with cardiac phenotypes of peripheral pulmonary artery stenosis and septal defects." (PMID 22136190, 2011). "We described previously that mice doubly heterozygous for Jag1 and Notch2 mutations are an excellent model for Alagille syndrome." (PMID 18365007, 2008).